CFL1 (cofilin 1)
Description:
Binds to F-actin and exhibits pH-sensitive F-actin depolymerizing activity. In conjunction with the subcortical maternal complex (SCMC), plays an essential role for zygotes to progress beyond the first embryonic cell divisions via regulation of actin dynamics. Required for the centralization of the mitotic spindle and symmetric division of zygotes (By similarity). Plays a role in the regulation of cell morphology and cytoskeletal organization in epithelial cells. Required for the up-regulation of atypical chemokine receptor ACKR2 from endosomal compartment to cell membrane, increasing its efficiency in chemokine uptake and degradation. Required for neural tube morphogenesis and neural crest cell migration (By similarity).
Synonyms: CFL; HEL-S-15; cofilin
Tractability: Small molecule: a structure with a bound ligand is known. Antibody: UniProt places it where antibodies can reach, with high confidence; its Gene Ontology location is reachable by antibodies, with medium confidence; the Human Protein Atlas places it where antibodies can reach. PROTAC: UniProt records ubiquitination sites on it; ubiquitination databases record sites on it; its protein half-life has been measured.
Gene: Protein-coding gene on chromosome 11 (65,823,022 to 65,862,026, reverse strand). Ensembl gene ENSG00000172757.
Subcellular location: Nucleus matrix; Cytoplasm, cytoskeleton; Cell projection, ruffle membrane; Cell projection, lamellipodium membrane; Cell projection, lamellipodium; Cell projection, growth cone; Cell projection, axon
Subcellular location (Human Protein Atlas): Plasma membrane
Pathways (Reactome):
Developmental Biology: EPHB-mediated forward signaling; Sema3A PAK dependent Axon repulsion
Immune System: Gene and protein expression by JAK-STAT signaling after Interleukin-12 stimulation; Regulation of actin dynamics for phagocytic cup formation
Hemostasis: Platelet degranulation
Signal Transduction: RHO GTPases Activate ROCKs
Gene Ontology:
Molecular function: actin filament binding; protein binding; actin binding; actin filament severing activity; phosphatidylinositol bisphosphate binding; protein phosphatase binding; signaling receptor binding
Biological process: actin filament depolymerization; host-mediated activation of viral process; regulation of dendritic spine morphogenesis; response to virus; actin cytoskeleton organization; actin filament fragmentation; actin filament severing; establishment of spindle localization; mitotic cytokinesis; negative regulation of apoptotic process; positive regulation of embryonic development; Rho protein signal transduction; actin polymerization or depolymerization; cellular response to epidermal growth factor stimulus; cellular response to ether; cellular response to hydrogen peroxide; cellular response to insulin-like growth factor stimulus; cellular response to interleukin-1; cellular response to interleukin-6; cellular response to tumor necrosis factor; hippocampus development; modification of postsynaptic actin cytoskeleton; modulation of chemical synaptic transmission; negative regulation of actin filament bundle assembly; negative regulation of actin filament depolymerization; and 19 more
Cellular component: cytoplasm; extracellular exosome; extracellular region; focal adhesion; membrane; nuclear matrix; vesicle; cytosol; lamellipodium; nucleus; actin cytoskeleton; axon; cell leading edge; cell-cell junction; cofilin-actin rod; cortical actin cytoskeleton; cytoskeleton; dendritic spine; filopodium; glutamatergic synapse; growth cone; lamellipodium membrane; mitochondrial membrane; neuronal cell body; postsynaptic density, intracellular component; and 2 more
Genetic constraint (gnomAD): Loss-of-function variants: 2 observed, 15.45 expected, observed/expected ratio (o/e) 0.13, 90% interval 0.052 to 0.41. The upper end of that interval is the gene's LOEUF score, 0.41, which puts it in group 1 of 6, group 1 being the genes least tolerant of losing a copy. Missense variants: 75 observed, 208.55 expected, observed/expected ratio (o/e) 0.36, 90% interval 0.3 to 0.44. Synonymous variants: 111 observed, 86.52 expected, observed/expected ratio (o/e) 1.28, 90% interval 1.1 to 1.5.
Homologues: Orthologues: chimpanzee CFL1 (99% identical), macaque CFL1 (99% identical), mouse Cfl1 (99% identical), guinea pig CFL1 (98% identical), rat Cfl1 (87% identical), tropical clawed frog cfl1 (78% identical), zebrafish cfl1 (75% identical), Drosophila melanogaster tsr (31% identical), Caenorhabditis elegans F53E2.2 (27% identical), Drosophila melanogaster CG6873 (25% identical), Caenorhabditis elegans unc-60 (24% identical). Paralogues in human: CFL2 (81% identical), DSTN (71% identical).
Diseases named in the same sentence as CFL1 in open-access papers:
CFL1 is named in the same sentence as 148 diseases in open-access papers, as found by Europe PMC text mining. Sharing a sentence is not in itself a finding about the gene and the disease. The quoted sentences say what the papers report.
breast cancer (25 papers, 2011 to 2025). A primary or metastatic malignant neoplasm involving the breast. "In conclusion, among the ABPs identified in this study as being associated with a strong metastatic potential of breast cancer cells, CFL1 showed the most robust results." (PMID 39281318, 2024). "Although overexpression of CFL1 in breast cancer tissue has been associated with poor prognosis and survival, to our knowledge serum levels of CFL1 were never assessed." (PMID 33267867, 2020). "Also, a high CFL1 mRNA level was associated with malignant breast cancer subtypes, and CFL1 expression was highest in breast cancer populations that formed metastases within 5 years." (PMID 39281318, 2024). "External validation revealed that CFL1 and TMSB15A had significant associations with consistent hazard ratios in two breast cancer cohorts, and among these, CFL1 exhibited the highest hazard ratios." (PMID 39281318, 2024). "It has been observed that altered CFL-1 expression is present in many tumor samples, such as breast cancer, thyroid cancer, renal cell carcinoma, OC, and oral squamous cell carcinoma." (PMID 37174083, 2023). "It was demonstrated that miR-342 inhibits the proliferation and migration of the triple negative breast cancer cell invasion by targeting cofilin-1 and promoting apoptosis which identifies miR-342 as a novel therapeutic target in breast cancer." (PMID 34678587, 2022). "They analysed the expression of cofilin-1 in tissue microarrays of 310 patients with various subtypes of breast cancer using immunohistochemistry." (PMID 34678587, 2022). "On the other hand, CFL-1 phosphorylation by activated ERK1/2 will be associated with EMT, poor prognosis and worse overall survival in breast cancer." (PMID 33805447, 2021). "High levels of both TLN1 and CFL1 are reported in the secretome of breast cancer cell lines (including, metastatic, triple-negative, MCF7 ER-positive, and triple-negative), confirming their release into the ECM." (PMID 33267867, 2020). "Cofilin 1 (CFL1) is an intracellular actin-modulating protein associated with EGF-stimulated chemotaxis and invadopodia localization in breast cancer cell invasion." (PMID 33267867, 2020). "Model 1 was built using three proteins previously identified as potential biomarkers of breast cancer in blood and/or tissue: Cofilin 1 (CFL1, LGGSAVISLEGKPL), Alpha-2-HS-glycoprotein (AHSG, HTFMGVVSLGSPSGEVSHPR), and Filamin A (FLNA, SPFSVAVSPSLDLSK)." (PMID 33267867, 2020). "Cofilin-1 expression level was significantly increased in breast cancer samples at TNM stages T0, T1 and T2 (based on tumor size (T stage))." (PMID 31700829, 2019). "Taking these findings together, our study suggests that CD74 promotes CFL1 phosphorylation in breast cancer cells." (PMID 27626171, 2016). "CFL1 was reported to be overexpressed in cells with high metastatic and invasion abilities, including hepatoma carcinoma, breast cancer and colon carcinoma cells." (PMID 25529407, 2015). "Our recent data using in vivo isolated breast cancer stem cells also exhibit lower CFL-1 levels and higher radioresistance than parental breast cancer cells (manuscript in preparation)." (PMID 25689427, 2015). "Among them apolipoprotein A-I and D, enolase 1, tumor rejection antigen (gp96) 1, transgelin 2, cofilin 1, profilin, heat shock proteins 70, and annexins 5 were found to be present in significant quantity in both types of breast cancer." (PMID 22110952, 2011). "Additionally, CFL-1 expression is increased in the invasive subpopulation of tumor cells in mammary tumors." (PMID 37174083, 2023). "Cofilin-1 was found to be upregulated in breast cancer tissues and cell lines." (PMID 34678587, 2022). "Finally, high expression of CAPN2 and aberrant activation of the LIMK1/CFL1 axis found in breast cancer have been positively correlated with cancer development and metastasis." (PMID 34381117, 2021).
breast cancer (continued). "CAPN2 might be an important target with therapeutic potential for the design of inhibitors of the LIMK1/CFL1 signaling pathway in breast cancer." (PMID 34381117, 2021). "Moreover, CD74 overexpression promoted the phosphorylation of the actin-severing protein cofilin (CFL1), resulting in actin polymerization in breast cancer cells." (PMID 27626171, 2016). "In addition, CFL1 was reported to be highly expressed in highly invasive cells, including breast cancer, colon cancer and malignant glioma cells." (PMID 25529407, 2015). "The mRNA levels and expression of cofilin-1 was higher in most tumor tissues, as compared to normal in various types of cancer, such as non-small cell lung cancer, prostate cancer, vulvar squamous cell carcinoma, hepatoblastoma, breast cancer, ovarian cancer, and bladder cancer." (PMID 40362336, 2025). "Thus, targeted inhibition of CFL1 might be a promising approach to treat malignant breast cancer cells." (PMID 39281318, 2024). "Among the identified genes, CFL1 (Gene Entrez ID 1072) and BRCA2 (Gene Entrez ID 675) were validated as the basal and luminal breast cancer gene markers." (PMID 34573857, 2021). "In basal breast cancer, PP2A appears to act as a metastasis promoter by activating cofilin-1 (CFL-1)." (PMID 32719745, 2020). "In summary, we demonstrate that CD74 promotes breast cancer cell metastasis, that CD74 and CD44 coordinately upregulate CFL1 phosphorylation through RHOA pathway, and that the repression of CD74 expression suppresses xenograft growth in vivo." (PMID 27626171, 2016). "It was found that proteins capable of inducing malignant transformation such as cofilin-1 were overexpressed in the EVs from the breast cancer cell line compared to the non-cancerous control cell line." (PMID 34678587, 2022). "Opposite effects have been reported for cell migration and metastasis of various cancers such as papillary thyroid and breast cancer, where overexpressed AURKA induced an up-regulation of SSH-1 expression, thus favoring the dephosphorylation and activation of CFL1." (PMID 35054947, 2022). "Cofilin 1 enhanced the migration and invasion capacities of T24 and RT4 cells, indicating that Cofilin 1 contributes to invasion and metastasis in bladder tumors as well as in mammary tumors." (PMID 29190896, 2017). "Moreover, RHOA is necessary for CFL1 phosphorylation and cell migration induced by CD74 in breast cancer cells." (PMID 27626171, 2016).
pancreatic cancer (15 papers, 2014 to 2025). "Other complexes notably involving cofilin 1 were found to be associated with pancreatic cancer." (PMID 32092936, 2020). "Turhani reported high CFL1 expression in OSCC, and they also identified associations with cancers of the pancreas, breast, and gallbladder." (PMID 40818124, 2025). "Similar to the results of this study, the anti-TAA autoantibodies of CFL1, EZR, CYPA have been shown certain diagnostic performance in esophageal cancer, pancreatic cancer, and breast cancer." (PMID 38684875, 2024). "Among them, the anti-TAA autoantibodies of CFL1, EZR, CYPA have been shown diagnostic potential in esophageal cancer, pancreatic cancer, and breast cancer." (PMID 38684875, 2024). "High-throughput analyses and screenings of pancreatic tissues suggest cofilin-1 (CFL1) as a biomarker for pancreatic cancer." (PMID 33578795, 2021). "As a first step in the depth-characterization of CFL1 in pancreatic cancer, we analyzed its expression in primary human pancreatic cancer and control tissues." (PMID 33578795, 2021). "This mechanistic model is able to predict the behavior of CFL1 and its effect on downstream targets in pancreatic cancer cells." (PMID 33578795, 2021). "In the presented gene regulatory network, the next protein being activated in the transition towards pancreatic cancer after CFL1 is STAT3 (time step 8)." (PMID 33578795, 2021). "Taken together, our results provide compelling evidence for an important, multi-faceted pro-oncogenic role of CFL1 in pancreatic cancer cells in vitro and in vivo." (PMID 33578795, 2021). "Here, we used a mechanistic model to unravel molecular tumor-promoting regulations of CFL1 in pancreatic cancer." (PMID 33578795, 2021). "In a recent research, LINC00941 was shown to enhance pancreatic cancer growth by competing with miR-335-5p to inhibit the ROCK1-mediated LIMK1/cofilin-1 signaling pathway." (PMID 34764994, 2021). "BrdU incorporation assays revealed inhibition of proliferation in CFL1 silenced pancreatic cancer cell lines cancer cell lines." (PMID 33578795, 2021). "According to the intervention screening, both induce apoptosis in combination with active CFL1 or active actin (which are both present in pancreatic cancer)." (PMID 33578795, 2021). "Systematic evaluation of global network dynamics over time showed that this model is able to recapitulate our previous observations in pancreatic cancers as well as for CFL1 silenced cells." (PMID 33578795, 2021). "Cofilin-1 (CFL1) overexpression in pancreatic cancer correlates with high invasiveness and shorter survival." (PMID 33578795, 2021). "Thereby, we identified CD44 as promising drug target for pancreatic cancer patients with high CFL1 expression." (PMID 33578795, 2021). "We present a Boolean network model which accurately reflects functional and molecular observations of pancreatic cancer with high cofilin-1 (CFL1) expression." (PMID 33578795, 2021). "Cofilin-1 involved in motility and invasion is up-regulated in pancreatic carcinoma tissues while muscle cofilin-2 was reported to be downregulated." (PMID 25188245, 2014). "Therefore, we first performed RNAi-based functional experiments with CFL1 in pancreatic cancer cells, which later served as a basis for a gene regulatory network model to unravel mechanistic regulations." (PMID 33578795, 2021). "This article presents a logical model of pancreatic cancer cells with high cofilin-1 expression." (PMID 33578795, 2021). "Here, we unraveled molecular tumor-promoting functions of CFL1 in pancreatic cancer." (PMID 33578795, 2021). "Hence, similar to other cancers, CFL1 silencing decreases infiltration and migration potential of pancreatic cancer cells." (PMID 33578795, 2021). "As expected, CFL1 expression was also high in all pancreatic cancer cell lines examined." (PMID 33578795, 2021). "High-throughput screenings of pancreatic cancers already suggested CFL1 as biomarker." (PMID 33578795, 2021).
pancreatic cancer (continued). "Even though our mechanistic model necessarily represents an oversimplification of complex cellular networks, we could show that it is able to reproduce the behavior of CFL1 in pancreatic cancer." (PMID 33578795, 2021). "However, our in-depth characterization of CFL1 in pancreatic cancer further supports a central and much more complex role of CFL1, including regulatory functions in proliferation and apoptosis inhibition." (PMID 33578795, 2021). "Finally, we identified the surface protein CD44 as a promising therapeutic target for pancreatic cancer patients with high CFL1 expression." (PMID 33578795, 2021). "Importantly, cofilin-1 play a role in multidrug resistance in pancreatic cancer, and platinum resistance in human lung adenocarcinoma cell lines, ovarian cancer, and tumor biopsies." (PMID 31700829, 2019). "Positive expression of UGP2 and CFL1 can serve a valuable prognostic factor in pancreatic cancer." (PMID 29347944, 2018). "Thus, our newly established gene regulatory model might be suitable to uncover mechanistic regulations behind the dynamics leading to the more severe phenotype of active CFL1 in pancreatic cancer." (PMID 33578795, 2021). "In pancreatic cancer, LINC00941 has shown to activate the LIMK1/Cofilin-1 pathway, which enhances cell proliferation and migration by regulating the actin cytoskeleton." (PMID 36869839, 2023). "In contrast to this, we did not observe induction of apoptosis after silencing of CFL1 in pancreatic cancer cells." (PMID 33578795, 2021). "None of the pancreatic cancer cell lines treated with CFL1 siRNA showed cleaved-caspase 3 or cleaved PARP activity–both indications for apoptosis - nor did any of the cells treated with non-silencing siRNA or untreated cells." (PMID 33578795, 2021). "This may explain why CFL1 knockdown already triggers apoptosis in other cancers but not in pancreatic cancer." (PMID 33578795, 2021). "Likewise, the CFL1 model is capable of reproducing the previously observed functional and molecular events in pancreatic cancer cells with and without RNAi-mediated knockdown of CFL1 expression." (PMID 33578795, 2021).